HMGA2 (high mobility group AT-hook 2)
Diseases named in the same sentence as HMGA2 in open-access papers (continued):
Sharing a sentence is not in itself a finding about the gene and the disease.
tumor (continued). "There are a number of tumor‐promoting factors in tumor cells such as IL‐17RB, IGF‐1R, MDR1, Bcl‐2, and HMGA2, among others, that can mediate resistance of cancer cells to DOX chemotherapy." (PMID 36684100, 2023). "IF staining indicated that CD44-positive cells are Hmga2+ and Spc−, supporting the idea of using CD44 to subset tumor organoid cells." (PMID 36993454, 2023). "This miRNA targets oncogenes and important genes for the initiation and progression of the tumor, including Myc, RAS, E2F1, E2F5, LIN28, ARID3B, PBX3, HMGA2 and long non-coding RNA H19." (PMID 36833380, 2023). "We also identified genes encoding membrane receptors (IL7R, OSMR, EGFR) and transcriptional regulators (BNC2, BNC1, HMGA2, KLF7, NR3C1) as enriched in Basal tumours." (PMID 36944729, 2023). "shHAGLROS promoted miR-206 expression, inhibited HMGA2 expression and repressed PTC tumor growth in mice." (PMID 38112616, 2023). "In xenograft tumours, GATM knockdown suppressed the expression of MYC, HMGA1, and HMGA2, and GAA diet feeding stimulated their expression." (PMID 37370109, 2023). "We found that the gene expression of SOSTDC1, HMGA2, and FHL1 was significantly higher in tumor tissues than their paired adjacent normal tissues from 31 PRCC patients in TCGA database, especially that of HMGA2 (p < 0.001)." (PMID 37283291, 2023). "Recent studies demonstrated that METTL3 indirectly promotes HMGA2 expression by regulating the m6A modification of circHPS5 and MALAT1 in tumor cells." (PMID 36945110, 2023). "By examining their expression in Xenabrowser, we found that HMGA2 and IL20RB were positively correlated with GRIN2D expression and highly expressed in PDAC tumor tissues." (PMID 37553583, 2023). "A study has indicated that in OSCC, the LIN28B-Let7 axis enhances tumor cell stemness and promotes tumorigenesis by mediating SOX2 expression through HMGA2." (PMID 37237385, 2023). "CRISPR knockout of both HMGA2 and EZH2 in the TNBC cell line MDA-MB-231 blocked primary tumor growth and lung metastasis and restored E-Cadherin in vivo." (PMID 36814601, 2023). "Let-7 serves as a potent tumor suppressor through post-transcriptional repression of a number of oncogenic mRNA targets including DICR1, ARID3B, HMGA2 and MYCN." (PMID 36505784, 2022). "Among the downregulated genes were several known to activate proliferation of tumor cells (NOTCH1, HMGA2, PTK2, FOSL1, GREM1 and EGR1)." (PMID 35885035, 2022). "Depletion of HMGA2 in exosomes derived from EBV-positive NPC cells attenuates endothelial cell dysfunction and tumor cell metastasis." (PMID 35388172, 2022). "Collectively, our results demonstrated that Hmga2 knockout in CRC cells inhibited TAM infiltration, M2 polarization, and CCL2 secretion in subcutaneous tumor models." (PMID 34976223, 2022). "The overexpression of several target genes and pathways, such as Liver Kinase B1 (LKB1), HMGA2, Wnt-β-catenin signaling pathway, and tensin 4 (TNS4) has been attributed to the downregulation of miR-150 and can lead to NSCLC tumor progression and metastasis." (PMID 36613642, 2022). "The increased TNF-α and decreased TGF-β secretion in Hmga2-KO tumor tissues was further confirmed by ELISA in both MC38 and CT26 subcutaneous tumor models." (PMID 34976223, 2022). "In summary, our present study demonstrated that overexpression of HMGA2 in CRC cells facilitated macrophage recruitment and M2 polarization via upregulating STAT3-mediated CCL2 secretion, thus promoting tumor immunosuppression in CRC." (PMID 34976223, 2022). "The let7 miRNA family has been described to play a tumor-suppressive role by targeting oncogenes such as RAS and HMGA2." (PMID 35741223, 2022). "Inhibition of HMGA2 blocks SNAIL1 (SNAI1) transcription and other mechanisms involved in tumour cell invasion and metastasis." (PMID 35203304, 2022).
tumor (continued). "Aiming to fill this gap, in the present study, we performed an in vivo experiment with the HMGA2-knockdown ACHN cells by stable RNAi-silencing, which were grown as tumor xenografts in nude mice." (PMID 35439951, 2022). "Our results show that knockdown of HMGA2 significantly inhibited the tumor growth of ACHN cells and HMGA2 regulates the expression of EMT-related genes in vivo." (PMID 35439951, 2022). "Within a complex tumour metastasis-enhancing network, the final result is that RKIP induces let-7, which is known to inhibit HMGA2 (high mobility group AT-hook 2)." (PMID 35203304, 2022). "The co-amplification of HMGA2, TSPAN31, and YEATS4 with MDM2 is frequently observed in DDLPS and is involved in tumor development." (PMID 34834427, 2021). "The let-7 family of miRNAs are well described tumor suppressors and are known to target several oncogenes including RAS, MYC and HMGA2." (PMID 33531067, 2021). "Expression levels of HMGA2 and PDCD10 in CHOL were significantly correlated with tumor infiltration by seven and nine immune cell types, respectively." (PMID 34831096, 2021). "Compared with the control group, tumour growth was inhibited in the ZFAS1 knockdown group from 25 to 35 days, and this inhibitory effect was reversed by HMGA2 plasmid." (PMID 34552050, 2021). "By targeting transforming growth factor-alpha (TGF-α), tribbles pseudokinase 1 (TRIB1), CCND2, and high-mobility group AT-hook 2 (HMGA2) and Src, miR-203, miR-224, miR-154, and miR-1, respectively, counteract EMT, tumor progression and metastasis." (PMID 33805590, 2021). "Accordingly, some genes (like HMGA2, MYO5B, and PAK6) had the opposite roles of AS events from the same parental gene in tumor and healthy tissues." (PMID 34628367, 2021). "Let-7b/f were proposed as tumor suppressor miRNAs, due to their negative regulation of the cell division cycle 34 (CDC34) and high mobility group AT-hook 2 (HMGA2) oncogenes." (PMID 34503164, 2021). "Let-7 miRNAs generally function as tumor suppressors to target multiple oncogenes, including RAS, HMGA2, c-Myc and CCND1." (PMID 34572067, 2021). "Compared with the sh-METTL3 + oe-NC group, tumor volume and weight in the sh-METTL3 + oe-HMGA2 group were significantly increased." (PMID 34419065, 2021). "In PDAC tumor-bearing xenografted mice, injection of LIN28B-positive sEVs activated LIN28B/let-7/high-mobility group AT-hook 2 (HMGA2)/platelet derived growth factor subunit B (PDGFB) signaling to facilitate PDAC liver metastasis." (PMID 34638330, 2021). "The TRIM71 protein, which regulates early development and differentiation, can act as a tumor suppressor by post-transcriptionally repressing LIN28B and modulating the let-7/Hmga2 axis." (PMID 34439740, 2021). "In this study, HMGA2 gene expression was significantly higher in the LUSC samples than matched normal samples, and tumor-gained H3K4me3 signals were found at the promoter and enhancer regions of this gene." (PMID 33916417, 2021). "Ex-miR-194-5p potentiates the survival of neighbor cancer cells, especially those with stem cell–like and tumor repopulating properties, by inducing a temporary G1/S arrest and upregulation of DNA damage response via direct inhibition of E2F3 and HMGA2." (PMID 34591242, 2021). "It increases high-mobility group AT-hook 2 (HMGA2) mediated EMT by antagonizing let-7 and promotes both tumor cell metastasis and invasion." (PMID 32257946, 2020). "HMGA1 and HMGA2 are involved in the EMT process, both during development (e.g., in NCCs) and in tumor progression." (PMID 31963852, 2020). "Altogether our results suggest a complex interplay among different species of RNAs, in which miR-370-3p displays a tumor-suppressor function in GSCs by targeting mRNAs involved in EMT and in hypoxia (i.e., HMGA2 and HIF1A, respectively)." (PMID 32443824, 2020).
tumor (continued). "Intriguingly, their respective antisense protein coding genes (HMGA2 for TROLL-2 and TRAF3IP2, also known as ACT1, for TROLL-3) are both known oncogenes supporting tumour growth and dissemination." (PMID 33056990, 2020). "Meanwhile, miR-182 inhibits BRCA1, a tumor suppressor involved in DNA repair, and MTSS1, a metastasis suppressor, and upregulates the EMT promoter HMGA2, thus increasing EOC cell invasiveness in vitro and tumor metastasis in vivo." (PMID 32993038, 2020). "Generally, miR-182-5p regulates the apoptosis of tumor cells by targeting certain special genes, such as FOXO1, MTSS1, HMGA2, CASP9, and FOXO3, and these target genes were also predicted by our experiment." (PMID 32090086, 2020). "We also identified the lncRNAs GATA6‐AS1 (GATA6 Antisense RNA 1) and HMGA2 (High Mobility Group AT‐Hook 2) within term C. In our data, GATA6‐AS1 was significantly downregulated in IVL tumor samples (P = .0246)." (PMID 32372565, 2020). "miR-16 is considered to be a critical tumour suppressor miRNA downregulated in many types of cancer, among the validated miRNAs targeting both HMGA1 and HMGA2." (PMID 31979076, 2020). "We demonstrated that HMGA2 reduction inhibited FN-RMS tumor growth in vivo and that ectopic HMGA2 expression resulted in tumor development in vivo." (PMID 32489328, 2020). "It has been reported that both HMGA1 and HMGA2 are high expressed in HGSOC and correlated with tumor progression and poor prognosis." (PMID 32127525, 2020). "The let-7 family is considered a tumor suppressor because it inhibits the expression of multiple oncogenes, including RAS, MYC, and HMGA2." (PMID 32089682, 2020). "The first clue was provided by the finding that sequences in the 3′UTR of both HMGA1 and HMGA2 mRNAs could negatively control the expression of these mRNAs, whereas the deletion of these sequences—mimicking cytogenetic aberrations found in human tumours—led to protein overexpression." (PMID 31979076, 2020). "HMGA2 involvement in EMT is very well documented in a variety of tumors, and we have discussed some of its involvement in tumor EMT and migration in connection with NCCs." (PMID 31963852, 2020). "Thus, HMGA2 may be useful in evaluating the tumor nature in biopsy specimens." (PMID 32351899, 2020). "Let-7 has a powerful tumor-suppressive capacity, including repression of oncogenes such as RAS and high mobility group AT-hook 2 (HMGA2) in humans." (PMID 32102476, 2020). "Altogether, our study demonstrated that VB promotes let‐7g‐5p expression, which down‐regulates HMGA2 via Wnt/β‐catenin signalling blockade, and results in inhibited GBM tumour cell proliferation and promoted autophagy." (PMID 32000296, 2020). "The tumor suppressor let-7a is delivered to the tumor and reduce the expression of RAS and HMGA2 inhibiting the malignant growth of cancer cells." (PMID 31835327, 2019). "The novel role of HMGA2 in enhancing PARP1 PARylation activity and reducing efficacy of olaparib in blocking PARP1 function and PARP1 DNA trapping is expected to impact on tumor cell viability." (PMID 30289618, 2019). "High mobility group AT-hook 2 (HMGA2), as a key transcriptional regulator, plays a pivotal role in embryogenesis, EMT and tumor cell metastasis." (PMID 35519367, 2019). "In contrast with miR‐9 expression, HMGA2, a potential target of miR‐9, was highly expressed in HCC cell lines and in clinical tumor samples when compared with normal controls." (PMID 31408273, 2019). "We identified HMGA2 as a new interaction partner of PARP1, as a modulator of DNA damage‐induced PARP1 activity, and as an ADP‐ribose acceptor in human tumor cells." (PMID 30289618, 2019). "Altogether, these data demonstrate that HMGA2 is vital for NF1 MPNST cell survival and that repression of HMGA2 leads to tumour cell apoptosis." (PMID 31053152, 2019). "HMGA2 was expressed in its full length in 14 UCS and 9 OCS; in the remaining tumours, it was expressed in its truncated form." (PMID 31217897, 2019).
tumor (continued). "Tumor, paired adjacent, and apparently normal tissue blocks were sectioned sequentially and processed for KLK6 and HMGA2 staining." (PMID 31692974, 2019). "Based on the sequencing data, four tumor differentiation related genes (JUB, HMGA2, FAM110B and MCM2) were selected to perform the expression validation by GEO database." (PMID 29596435, 2018). "Let-7 is known to inhibit EMT by suppressing the high-mobility group AT-hook 2 (HMGA2) gene that activates the expression of SNAIL and TWIST to inhibit tumor growth and metastasis." (PMID 30393570, 2018). "RKIP-mediated HMGA2 downregulation also directly inhibited the expression of the pro-metastatic factor SDC2 independently of miR-200b, resulting in suppression of tumor survival and metastasis." (PMID 30149591, 2018). "Let-7 exerts its tumor suppressor function in part by inhibiting the expression of numerous oncogenes such as MYC, RAS, YAP1, HMGA2, and CDK6 and by altering cellular bioenergetics, including glucose metabolism." (PMID 30057901, 2018). "Tumours and cancer cell lines express at least one type of HMGA proteins (HMGA1 or HMGA2) and show a high level of oncogenic transformation." (PMID 29853899, 2018). "The expression levels of JUB, HMGA2 and MCM2 were increased gradually along with the tumor differentiation grades." (PMID 29596435, 2018). "In conclusion, our study identifies let-7c as a novel tumor suppressor of HNSCC that inhibits cell proliferation, migration, and EMT through repression of IGF1R and HMGA2 expression." (PMID 29507664, 2018). "It is known that HMGA2 overexpression is correlated with the down-regulation of let-7 miRNAs and with overexpression of LIN28B in several tumor types." (PMID 29383160, 2017). "As tumor suppressors, let-7 miRNAs repress several oncogenes including K-RAS, C-MYC, HMGA2 and cell cycle factors (Cyclin D1, D2; Roush and Slack, 2008)." (PMID 28400788, 2017). "We extended the studies to investigate nuclear expression of active Src, HMGA2, and SMYD3 expression in human PDAC tumor samples." (PMID 26695438, 2016). "Let-7 acts as a tumor suppressor miRNA and has been reported to modulate CSC self-renewal and mesenchymal transformation by targeting HMGA2." (PMID 27486821, 2016). "In this study we explore the significance of MYCN, HMGA2, CDKN2A and DICER1 in NSCLC tumours by gene expression analysis." (PMID 26858029, 2016). "The expression levels of anti-Let-7 target genes (in humans: HMGA2, IGF2BP2, and LIN28B; in mice: Igf2bp2, Nras, and Tgfbr1) were examined in each tumor mass and brain tissue from mice." (PMID 27102443, 2016). "Gene expression of MYCN, HMGA2, CDKN2A and DICER1 were investigated with RT-qPCR in surgically resected NSCLC tumour tissue from 175 patients." (PMID 26858029, 2016). "Three human target genes of anti-Let-7 (HMGA2, LIN28B, and IGFBP2) were upregulated in both the tumor core and peripheral tumor region after ITu injection only." (PMID 27102443, 2016). "Several independent studies have indicated that let-7 members act as tumor suppressors on various tumor types by targeting KRAS and HMGA2 oncogenes." (PMID 26701848, 2016). "In breast tumors, increased Wnt/β-catenin signaling was shown to up-regulate HMGA2, promote EMT transformation, and increase tissue invasion of tumor cells." (PMID 26799419, 2016). "It has been described that up-regulation of HMGA2 can activate the Snail, Twist and ZEB families expression and induce EMT process, which leads to tumor metastasis in various cancers." (PMID 26818837, 2016). "To determine the HMGA2 expression levels in these CRC patients, we first analyzed the gene expression of HMGA2 in 132 CRC tumor samples: 67 primary CRC tissues, 65 metastatic tissues, and nine normal colon controls." (PMID 26893968, 2016). "Then, we compared the mRNA levels of several TGF-β-related EMT-regulators including SNAI1, SNAI2, HMGA2, FOSL1, SP1, ZEB1, ZEB2 (SIP1), and TWIST1 in primary tumor tissues of MDA-MB-231-xenografted mice." (PMID 26462028, 2015).
tumor (continued). "SNP array identified frequent shared copy number events in all three tumor regions including FGFR1 amplification at chromosome 8p11.23 and classical CDK4, HMGA2 and MDM2 amplification at chromosome 12q13-15 region and deletion of TP53BP1 at chromosome 15q15." (PMID 26643872, 2015). "In agreement with our previous data for the parental cell line MDA-MB-231, as well as for other tumor cell lines, knockdown of TRAIL-R2 resulted in decreased expression of HMGA2, and correspondingly, decreased proliferation." (PMID 25909161, 2015). "Here, we describe a new epigenetic role for HMGA2, which follows the actions that HMGA2 initiates via the EMT-TFs, thus achieving sustained silencing of E-cadherin expression and promoting tumour cell invasion." (PMID 25492890, 2015). "The reduced HMGA2 expression and the reversal of the EMT phenotype observed in this study likely contribute to the chemosensitization of tumor cells." (PMID 25946136, 2015). "In this cellular compartment, TRAIL-R2, acting as a negative regulator of let-7 miRNA maturation, increases the expression of the respective targets high mobility group AT-hook 2 (HMGA2) and lin-28 homolog B (Lin28B), and enhances tumor cell proliferation." (PMID 25909161, 2015). "As a transcription factor, HMGA2 cooperates with transforming growth factor β in inducing Snail 1 expression, a zinc-finger transcription factor crucially involved in EMT and tumor progression." (PMID 25946136, 2015). "In contrast, miR-33b knockdown or HMGA2, Twist1 or ZEB1 overexpression significantly attenuated the effect of cordycepin on lifespan of tumor-bearing mice." (PMID 25868853, 2015). "HMGA2 disrupts binding of CTCF, a protein involved in maintenance of chromatin topology which insulates tumour suppressor genes and which has an inverse occupancy pattern with DNA methylated regions." (PMID 25492890, 2015). "HMGA2/HPRT expression ranged from 0.31 to 1 within the control group, and from 3.69 to 80.7 within the tumours." (PMID 25245141, 2014). "HMGA2 was up-regulated when GUSB and HPRT were used as endogenous control genes within the tumour samples when compared to the non neoplastic controls." (PMID 25245141, 2014). "HMGA2 was up-regulated when GUSB and HPRT were used as endogenous control genes within the tumour and cell line samples when compared to the non neoplastic samples." (PMID 25245141, 2014). "Cellular levels of HMGA2 directly correlate with ALDH activity in breast cancer and contribute to tumor migration and resistance toward DNA-damaging agents." (PMID 24723911, 2014). "HMGA2/HPRT expression levels ranged between 1 and 31.1 within the control group, 24.1 and 3778 within the tumour group, and 226 to 561 within the cell culture samples." (PMID 25245141, 2014). "Screenings as done herein exemplarily for the HMGA2 regulator let-7a and the HMGA2 targets HMGA1, SNAI1, SNAI2 and CDH1 will help to reveal the tumour acting mechanisms." (PMID 24914948, 2014). "HMGA2/GUSB values ranged between 1 and 26.8 in the control samples, 44.4 and 2330 in the tumour samples, and 319 and 1092 within the cell culture samples." (PMID 25245141, 2014). "In summary, Wnt10bLacZ-driven tumours are devoid of hormone receptors and HER2 expression, with specific expression of HMGA2 in tumour tissue only." (PMID 23307470, 2013). "In this region, there are important oncogenes such as CHOP (DDIT3), GLI, MDM2, CDK4, SAS, HMGA2, but also the HOXC locus, involved in development and tumor progression." (PMID 24085196, 2013). "Next we illustrate that in our cohort of TNBC samples HMGA2, like WNT10B, has predictive value for tumour size >1.5 cm (n = 45, τ = 0.33, p = 0.007) and high nuclear grade status 3 (n = 26, τ = 0.37, p = 0.047)." (PMID 23307470, 2013). "There is twice as much Hmga2 expression in both primary tumour cells and (Lin−) LacZ+ FACS-sorted tumour cells, than the Hmga1 expression profile in the same cells." (PMID 23307470, 2013).